ZBTB32 (zinc finger and BTB domain containing 32)
Description:
DNA-binding protein that binds to the to a 5'-TGTACAGTGT-3' core sequence. May function as a transcriptional transactivator and transcriptional repressor. Probably exerts its repressor effect by preventing GATA3 from binding to DNA. May play a role in regulating the differentiation and activation of helper T-cells (By similarity).
Synonyms: FAZF; TZFP; ZNF538; FAXF; Rog; mynn
Tractability: No criterion of Open Targets' tractability assessment is met for any kind of drug.
Target class: Transcription factor
Gene: Protein-coding gene on chromosome 19 (35,704,558 to 35,717,048, forward strand). Ensembl gene ENSG00000011590.
Subcellular location: Nucleus
Gene Ontology:
Molecular function: DNA-binding transcription repressor activity, RNA polymerase II-specific; protein binding; sequence-specific double-stranded DNA binding; DNA binding; DNA-binding transcription factor activity, RNA polymerase II-specific; RNA polymerase II cis-regulatory region sequence-specific DNA binding; zinc ion binding
Biological process: negative regulation of transcription by RNA polymerase II; regulation of cytokine production; regulation of immune system process; negative regulation of DNA-templated transcription
Cellular component: nucleus; chromatin; nucleoplasm
Genetic constraint (gnomAD): Loss-of-function variants: 28 observed, 46.12 expected, observed/expected ratio (o/e) 0.61, 90% interval 0.45 to 0.83. The upper end of that interval is the gene's LOEUF score, 0.83, which puts it in group 3 of 6, group 1 being the genes least tolerant of losing a copy. Missense variants: 587 observed, 643.17 expected, observed/expected ratio (o/e) 0.91, 90% interval 0.85 to 0.98. Synonymous variants: 283 observed, 263.46 expected, observed/expected ratio (o/e) 1.07, 90% interval 0.97 to 1.18.
Homologues: Orthologues: chimpanzee ZBTB32 (99% identical), macaque ZBTB32 (95% identical), dog ZBTB32 (78% identical), pig ZBTB32 (75% identical), rabbit ZBTB32 (72% identical), rat Zbtb32 (69% identical), mouse Zbtb32 (69% identical), zebrafish mynn (20% identical). Paralogues in human: ZBTB16 (32% identical), PATZ1 (15% identical), PRDM1 (14% identical), HIC1 (14% identical), HIC2 (14% identical), ZNF143 (13% identical), ZBTB20 (12% identical), ZNF76 (12% identical), ZBTB7C (12% identical), PRDM14 (12% identical), ZBTB42 (12% identical), ZBTB18 (11% identical), and 24 more.
Diseases named in the same sentence as ZBTB32 in open-access papers:
ZBTB32 is named in the same sentence as 25 diseases in open-access papers, as found by Europe PMC text mining. Sharing a sentence is not in itself a finding about the gene and the disease. The quoted sentences say what the papers report.
breast carcinoma (4 papers, 2015 to 2021). "Modulation of GATA3 by ZBTB32 in turn caused the development of aggressive breast cancers." (PMID 31787845, 2019). "By targeting the Zpo2 to GATA3 promoters, ZBTB32 promotes the deregulation of GATA3 target genes, leading to the progression of aggressive breast cancer." (PMID 35095893, 2021).
viral infections (3 papers, 2017 to 2019). "Overall, these results indicate that ZBTB32 is induced early and functions to limit effector T cell responses during acute virus infections." (PMID 28827827, 2017). "After acute virus infection, CD8+ T cells deficient in ZBTB32 showed enhanced virus-specific CD8+ T cell responses, and generated increased numbers of virus-specific memory cells; in contrast, persistent expression of ZBTB32 suppressed memory cell formation." (PMID 28827827, 2017). "Overall, these results indicate that ZBTB32 functions together with Blimp-1 to limit both effector T cell responses and memory development during acute virus infections." (PMID 28827827, 2017). "In contrast, ZBTB32 (zinc finger and BTB domain containing 32) is another transcription factor co-expressed with Blimp-1 and limits CD8+ T cell memory development during both acute and chronic viral infections." (PMID 31379821, 2019). "Here we addressed the function of ZBTB32 in CD8+ T cell responses to both acute and chronic virus infections." (PMID 28827827, 2017). "We found that mice deficient in Zbtb32 generated an enhanced anti-viral CD8+ T cell response during acute virus infection and had increased memory CD8+ T cell populations; conversely the sustained expression of Zbtb32 in virus-specific CD8+ T cells dampened the anti-viral T cell response." (PMID 28827827, 2017). "The dysregulation of CD8+ T cell responses in the absence of ZBTB32 was catastrophic, as Zbtb32-/- mice succumbed to a systemic viral infection and showed evidence of severe lung pathology." (PMID 28827827, 2017). "Unlike the transient expression of ZBTB32 in CD8+ T cells responding to acute virus infection, Blimp-1 expression is maintained in virus-specific cells well into the memory time points." (PMID 28827827, 2017). "Thus, ZBTB32 does not limit recall responses to a number of physiological acute challenges, but does restrict antibody levels during chronic viral infections that periodically engage memory B cells." (PMID 31649328, 2019). "Our data show that ZBTB32 plays a unique non-redundant role in limiting T cell responses and memory generation during acute virus infection, and that this regulation is essential to prevent lethality in a model of persistent virus infection." (PMID 28827827, 2017).
cytomegalovirus infection (2 papers, 2019). A herpesvirus infection caused by Cytomegalovirus. "Furthermore, the transcription factor ZBTB32, which is associated with adaptive NK cell responses following murine cytomegalovirus infection, was also upregulated in CD49a+ compared to CD49a- NK cells from PBC patients (p < 0.001, FDR < 0.01)." (PMID 31803181, 2019).
anemia (1 paper, 2016). A reduction in the number of red blood cells, the amount of hemoglobin, and/or the volume of packed red blood cells. "Zbtb32 is a Zinc Finger and BTB Domain Containing 32 gene that was originally identified as a transcriptional repressor protein that interacts with several proteins including the Fanconi anemia group C protein and PLZF." (PMID 27563627, 2016).
autoimmune disease (1 paper, 2018). A disorder resulting from loss of function or tissue destruction of an organ or multiple organs, arising from humoral or cellular immune responses of the individual to their own tissue constituents. "The available literature corroborated these findings but did not provide insight into how Zbtb32 might control T cell development and tolerance in a spontaneous autoimmune disease such as T1D9–11,27." (PMID 29707204, 2018).
autoimmune encephalitis (1 paper, 2018). Inflammation of the brain secondary to an immune response triggered by the body itself. "Interestingly, the role of Zbtb32 in immune tolerance was examined in the BALB/c strain by using the Experimental Autoimmune Encephalitis (EAE) model." (PMID 29707204, 2018).
Autoimmunity (1 paper, 2021). The occurrence of an immune reaction against the organism's own cells or tissues. "This memory subset is known to be associated with chronic infection and autoimmunity and was found in the ZBTB32+/CD27low memory compartment of population A1." (PMID 34723157, 2021).
COVID-19 (1 paper, 2022). A disease caused by infection with severe acute respiratory syndrome coronavirus 2. "In single cell studies, transcripts of ZBTB32 were enriched in T follicular helper cells and were also expressed at significantly higher levels in hospitalized COVID-19 patients." (PMID 35708486, 2022).
diabetes (1 paper, 2018). "Furthermore, our results showed that overexpression of Zbtb32 delayed diabetes onset, limited T-cell proliferation, and decreased IFNγ production from autoreactive T cells in an adoptive transfer model of T1D6." (PMID 29707204, 2018). "In addition, transient overexpression of Zbtb32 in islet-specific CD4 T cells delayed diabetes development, and decreased both proliferation and IFNγ production in islet-specific CD4+ T cells." (PMID 29707204, 2018). "We hypothesized that the systemic loss of Zbtb32 in NOD mice would lead to increased T cell activation and increased diabetes pathogenesis." (PMID 29707204, 2018). "Taken together, our results show that the systemic loss of Zbtb32 in NOD mice does not lead to a hypersensitive T cell phenotype and increased diabetes pathogenesis." (PMID 29707204, 2018). "To test the hypothesis that absence of Zbtb32 would increase diabetes pathogenesis in NOD mice, we monitored diabetes via blood glucose levels in NOD.Zbtb32-/- mice and their control littermates for up to 35 weeks for both female and male mice." (PMID 29707204, 2018). "Furthermore, Zbtb32 was preferentially induced in autoreactive CD4 T cells stimulated by these tolerogenic DCIR2+ DCs, and overexpression of Zbtb32 in islet-specific T cells inhibited the diabetes development by limiting T cell proliferation and cytokine production." (PMID 29707204, 2018).
diffuse large B-cell lymphoma (1 paper, 2021). "For instance, human activated B cells in diffuse large B-cell lymphoma (DLBCL) carry ZBTB32 as the most consistently expressed gene." (PMID 35095893, 2021).
Dystonia (1 paper, 2023). An abnormally increased muscular tone that causes fixed abnormal postures. "Within the common overlapping region, ZBTB32 is another new candidate gene in our cohort with no previous report of association with dystonia or neurodevelopmental disorder patients." (PMID 36959829, 2023).
germ cell tumor (1 paper, 2022). A benign or malignant, gonadal or extragonadal neoplasm that originates from germ cells. "In germ-cell tumors, ZBTB32 transcription is suppressed to an almostundetectable level,while ZNF473 transcription is decreased to thevalues characteristic of other tissues." (PMID 36348719, 2022). "The samples of normal tissues adjacent to germ cell tumors are characterized bya large spread in the ZBTB32 and ZNF473 transcription levels from values closeto those in the control samples (samples 5N, 8N, and 14N) to onescharacteristic of tumors (samples 7N and 21N)." (PMID 36348719, 2022). "Wehave experimentally confirmed a decrease in the transcription level of twoselected genes (ZBTB32 and ZNF473) in germ cell tumors." (PMID 36348719, 2022).
Hepatic steatosis (1 paper, 2021). Steatosis is a term used to denote lipid accumulation within hepatocytes. "Hepatic steatosis in livers of ZBTB32+/+ and ZBTB32−/− mice 24h after starvation was assessed through LipidTOX staining and through quantification of the amounts and the size of individual LDs." (PMID 34337361, 2021).
influenza infection (1 paper, 2019). "To determine if ZBTB32-deficiency extends the duration of antibody responses against influenza, we adopted an infection and heterologous vaccination model." (PMID 31649328, 2019). "Indeed, we observed no role for ZBTB32 in restricting antibody responses in mouse models of influenza infection and vaccination, nor in responses to intestinal bacteria." (PMID 31649328, 2019).
lymphoma (1 paper, 2020). A malignant (clonal) proliferation of B- lymphocytes or T- lymphocytes which involves the lymph nodes, bone marrow and/or extranodal sites. "ZBTB32 showed significantly higher expression in SMZL cases with lymphoma symptoms present (p = 0.04)." (PMID 32457837, 2020).
multiple myeloma (1 paper, 2019). "We first considered the possibility that ZBTB32 acts as a tumor suppressor of multiple myeloma, a plasma cell malignancy." (PMID 31649328, 2019).
tumor (6 papers, 2020 to 2024). "The expression of ZBTB32 and CCL5 was also determined by western blot analysis using tumor masses, and the mutation of di‐methylated Lys148 inhibited ZBTB32 and CCL5 expression, which was consistent with the results in A549 and H460 cells." (PMID 38873823, 2024). "In this regard, the similarity of the transcription profiles for ZBTB32 andZNF473 in germline samples between normal and tumor tissue is important; itsuggests the consistency of their transcription." (PMID 36348719, 2022). "In general, a significant decrease in the ZNF473 and ZBTB32 transcriptionlevels is observed in tumor as compared to healthy tissue (theMann–Whitney p-value is < 0.02 in both cases and >0.4 in ZNF446).These genes can act as markers for germ cell-derived tumors." (PMID 36348719, 2022). "Cd274 and Zbtb32 negatively regulate immunity, and S100a4, Rap1gap, Armc3, and Prkar2b promote tumor metastasis, This was consistent with the emergence of immunosuppression in the later stages of E. granulosus infection and with the hydatid cyst metastasis." (PMID 36569953, 2022). "In our study, ZBTB32 was found to be downregulated in OS samples, pointing at this gene as a potential tumor suppressor." (PMID 35095893, 2021). "The expression levels of ZBTB32 and DEPTOR were higher in normal tissues than in tumor tissues (P <0.001), while the opposite was true for SPAG4 expression (P <0.001)." (PMID 35095893, 2021). "In paired samples with a highlevel of normal transcription (pairs No. 8, 14, and 32), ZBTB32 and ZNF473transcription in the tumor is downregulated at least eight and three times,respectively." (PMID 36348719, 2022). "In tumor tissues, SPAG4 was overexpressed while ZBTB32 and DEPTOR were downregulated." (PMID 35095893, 2021). "Increased ZBTB32 expression has been identified among memory B-cells, and thus, its increased expression among symptomatic patients may be due to an increased presence of the memory B-cell based SMZL cells, a commonly proposed cell-type of primary SMZL tumor cells." (PMID 32457837, 2020).
infection (5 papers, 2016 to 2020). The state of being infected such as from the introduction of a foreign agent such as serum, vaccine, antigenic substance or organism. "Serum levels of MCMV DNA were similar between ZBTB32-deficient and –sufficient chimeras at week 1 post-infection, arguing against differences in viral load." (PMID 31649328, 2019). "The absence of Prdm1 attenuated ZBTB32 binding to the regulatory regions of Eomes and Cd27 at day 7 post-LCMV-Armstrong infection, and in reciprocal fashion, the Zbtb32-deficiency attenuated Blimp-1 binding (Amp1 in Eomes or Cd27)." (PMID 28827827, 2017). "When Zbtb32-/- mice were infected with high-dose clone 13 (2x106 pfu/mouse), approximately 70% of the mice succumbed by two weeks post-infection (top), and showed more severe weight loss than controls (bottom)." (PMID 28827827, 2017). "Chronic infection of Zbtb32−/− chimeras with murine cytomegalovirus led to nearly 20-fold higher antigen-specific IgG2b levels relative to controls by week 9 post-infection, despite similar viral loads." (PMID 31649328, 2019). "Antibody responses were similar against recombinant A/PR8 hemagglutinin (HA) protein between Zbtb32+/+ and Zbtb32−/− littermates through 12 weeks post-infection." (PMID 31649328, 2019). "Zbtb32-/- or WT P14 cells were sorted at day 30 post-primary LCMV-Armstrong infection, and equal numbers were adoptively transferred into naïve hosts, which were then challenged with LCMV-Armstrong." (PMID 28827827, 2017). "Next, we compared the CD8+ T cell responses of Zbtb32-/- versus wild type (WT) mice following LCMV-Armstrong infection." (PMID 28827827, 2017). "By day 15 post-infection, Zbtb32-/- P14 cells were enriched in memory precursor effector cells (MPEC; IL-7Rhi KLRG-1lo) and a greater proportion expressed CD27, CXCR3 and CD62L compared to WT controls (bottom)." (PMID 28827827, 2017). "In this study, MCMV-specific Zbtb32-/- CD8+ T cells showed enhanced expansion compared to controls at D7 post-infection, indicating a CD8+ T cell-intrinsic role for ZBTB32." (PMID 28827827, 2017). "Zbtb32-deficient CD8+ T cells were found to have enhanced responses to MCMV infection, whereas the opposite effect was observed in NK cells responding to the infection." (PMID 28827827, 2017). "Moreover, in order to form NK cell memory, NK cells require Zbtb32 to undergo a proliferative burst and clonal expansion in response to infection, require BNIP3 and BNIP3L -dependent clearance of damaged mitochondria by autophagy, and require pro-apoptotic factor Bim for contraction." (PMID 32849653, 2020). "At weeks 1–3 post-infection, MCMV-specific IgG2b levels were similar in Zbtb32−/− chimeras relative to Zbtb32+/+ controls." (PMID 31649328, 2019). "At days 9 and 15, we observed a higher proportion and absolute number of Zbtb32-/- compared to WT P14 cells, as well as a greater proportion of Zbtb32-/- P14 cells expressing the memory markers CD27 and CXCR3 at day 9 post-infection (top)." (PMID 28827827, 2017). "After infection, we found that Zbtb32-/- mice had higher proportions and absolute numbers of LCMV-specific CD8+ T cells at days 8 and 45 post-infection, a result confirmed by ex vivo IFNγ production." (PMID 28827827, 2017). "We found that the transcript levels for Zbtb32 were substantially elevated in Prdm1-/- CD44hi CD8+ T cells isolated at days 8 and 14 post-LCMV-Armstrong infection compared to WT controls." (PMID 28827827, 2017). "To determine the function of ZBTB32 in CD8+ T cells, we first analyzed the kinetics of Zbtb32 mRNA expression in CD8+ T cells responding to acute LCMV-Armstrong infection, and found a sharp peak of maximal expression at day 6 post-infection." (PMID 28827827, 2017). "CD4+ T cell-depletion of Zbtb32-/- mice and WT controls prior to infection with clone 13 did not alter the survival of Zbtb32-/- mice, although it did lead to a less severe loss in body weight of both WT and Zbtb32-/- clone 13-infected mice." (PMID 28827827, 2017).
infection (continued). "In Zbtb32-/- mice, virus-specific CD8+ T cells are more numerous and less exhausted as indicated with reduced expression of exhaustion markers, correlating with a reduction in viral titers in the spleen at day 10 post-high-dose LCMV-clone 13 infection." (PMID 28827827, 2017). "Finally, an infection and heterologous booster vaccination model revealed no role for ZBTB32 in restraining primary or recall antibody responses against influenza viruses." (PMID 31649328, 2019). "Thus, it seems unlikely that recall responses to these acute infections would dramatically alter the content of pre-existing plasma cells, even in the absence of ZBTB32." (PMID 31649328, 2019).
ZBTB32 also shares sentences with these, for which no sentence is quoted: cancer (2 papers); colon cancer (1); Fanconi anemia (1); leukemia (1); neurodevelopmental disorder (1); osteosarcoma (1); Type 1 diabetes (1).